ATF3 (activating transcription factor 3)
Diseases named in the same sentence as ATF3 in open-access papers (continued):
Sharing a sentence is not in itself a finding about the gene and the disease.
pulmonary fibrosis (12 papers, 2018 to 2026). Chronic progressive interstitial lung disorder characterized by the replacement of the lung tissue by connective tissue, leading to progressive dyspnea, respiratory failure, or right heart failure. "A conditional deficiency of ATF3 in AT2 cells protects mice from bleomycin-induced pulmonary fibrosis." (PMID 38625722, 2024). "ATF3 was found to be significantly upregulated in lung tissues from mice with bleomycin‐induced pulmonary fibrosis and in patients with rheumatoid arthritis‐associated interstitial lung disease." (PMID 37773692, 2023). "Activating transcription factor 3 expression increases with age and fibrosis, suggesting that this factor may play a crucial role in age‐related increased susceptibility to mitochondrial dysfunction and lung fibrosis." (PMID 29363258, 2018). "Recent findings indicate that activating transcription factor 3 (ATF3) can stimulate LINC00941/lncIAPF to promote the differentiation of fibroblasts into myoblasts by inhibiting ELAVL1/HuR-dependent autophagy in pulmonary fibrosis." (PMID 39612365, 2024). "In summary, C-PC alleviates pulmonary fibrosis through the ATF3/Smad3-lncIAPF-HuR signal pathway that targets autophagy and can be a potential drug for treating pulmonary fibrosis." (PMID 39039254, 2024). "In summary, C-PC alleviates pulmonary fibrosis through the ATF3/Smad3-lncIAPF-HuR signal pathway that targets autophagy." (PMID 39039254, 2024). "Our previous study has shown that activating transcription factor 3 (ATF3)-activated lncIAPF-HuR complex accelerates pulmonary fibrosis by blocking autophagy." (PMID 38147026, 2023). "In summary, these data suggest a role for ATF3 upregulation in the pathogenesis of lung fibrosis and in the aging lung." (PMID 29363258, 2018). "Conditional type II lung epithelial cells ATF3 knockout mice are protected from severe lung fibrosis induced by bleomycin showing a better outcome measured by pro‐fibrotic, pro‐inflammatory, and senescence markers while preserving PINK1 expression in the lung." (PMID 29363258, 2018). "Altogether, these data suggest that ATF3, via regulation of PINK1, has an important role in the AECIIs susceptibility to lung injury, senescence, and development of lung fibrosis." (PMID 29363258, 2018). "In studies of pulmonary inflammation and pulmonary fibrosis induced by inhaled silica particles, crystalline silica induced more intense stress‐related ATF3 gene expression and cytokine and chemokine secretion in primary human bronchial epithelial cells and mouse alveolar epithelial cells." (PMID 37773692, 2023). "ATF3 in type II lung epithelial cells accelerates PQ-induced lung fibrosis in mouse." (PMID 34580234, 2021). "Furthermore, conditional deletion of ATF3 in type II lung epithelial cells protects mice from bleomycin‐induced lung fibrosis." (PMID 29363258, 2018). "This connection may be critical in devising strategies designed to augment PINK1 expression or inhibit ATF3 levels to lessen severity of pulmonary fibrosis, especially in the context of the aging lung." (PMID 29363258, 2018). "Moreover, the small-molecule inhibitor Itraconazole, which targets the binding site of ATF3 and importin α, could reduce ATF3 nuclear entry, macrophage senescence, and pulmonary fibrosis (PF)." (PMID 42160006, 2026). "Most of the significantly enriched TFs related to pulmonary fibrosis included STAT3, FOXP1, JUNB, ATF3, FosL2, BATF, Fra2 and AP‐1." (PMID 40464702, 2025). "The Net-M5 detected genes involved in lung fibrosis (CXCL8 and IL1B), VEGFA-VEGFR2 signaling (NR4A1 and CBL), and TGF-β signaling (JUNB and ATF3)." (PMID 38259488, 2023). "Furthermore, naringin modulates the activating transcription factor 3/PTEN-induced kinase 1 (ATF3/PINK1) pathway and enhances mitophagy in lung tissues, resulting in the alleviation of bleomycin-induced idiopathic pulmonary fibrosis." (PMID 38399736, 2024).
pulmonary fibrosis (continued). "Recent studies have shown that ATF3 plays a critical role in many inflammatory pulmonary diseases, including acute lung injury (ALI)/acute respiratory distress syndrome (ARDS), chronic obstructive pulmonary disease (COPD), and pulmonary fibrosis (PF)." (PMID 37773692, 2023). "However, the expression and function of ATF3 in pulmonary fibrosis have not been widely explored." (PMID 39039254, 2024).
metabolic syndrome (11 papers, 2013 to 2025). A cluster of metabolic risk factors for CARDIOVASCULAR DISEASES and TYPE 2 DIABETES MELLITUS. "The authors concluded that ATF3 deficiency is involved in the pathogenesis of metabolic syndrome." (PMID 37049617, 2023). "Together, we identified that ethanol-induced Atf3 fosters β-cell dysfunction via Gck down-regulation and that its loss ameliorates metabolic syndrome and could be a potential therapeutic target in treating type 2 diabetes." (PMID 25074928, 2014). "Some studies have reported the role of ATF3 in the pathogenesis of metabolic syndrome induced by a high-fructose diet." (PMID 37049617, 2023). "Remarkably, in dyslipidemia, there was a reduction in the expression of inflammatory genes (e.g. ATF3, DUSP2 and PTGS2)." (PMID 26083362, 2015). "In vivo Atf3 silencing ameliorates ethanol-mediated metabolic syndrome and pancreatic β-cell dysfunction." (PMID 25074928, 2014). "In our previous study, ATF3 deficiency in mice results in higher serum levels of triglycerides, glucose, insulin, inflammatory cytokines (ICAM-1 and TNF-α), and increasing visceral adiposity, similar to metabolic syndrome." (PMID 36145135, 2022). "This resembled metabolic syndrome and indicated that ATF3 could be involved in regulating lipogenic properties." (PMID 36145135, 2022). "Nevertheless, we propose that in vivo Atf3 silencing may be sufficient to improve metabolic syndrome and pancreatic β-cell dysfunction by ameliorating ethanol-induced Gck down-regulation." (PMID 25074928, 2014). "Thus, ATF3 is involved in various vascular functions, including atherogenesis, through its role in the regulation of various processes related to hyperglycemia, dyslipidemia, and the immune response." (PMID 37189834, 2023). "Additionally, our findings suggest that strategies based on the inhibition of Atf3 may be of benefit in the treatment of ethanol-mediated glucose impairment and metabolic syndrome." (PMID 25074928, 2014). "Among these, several transcription factors stand out for their close connection to cyclic AMP signaling (ATF1, ATF3, and CREB1), although their relationship to metabolic syndrome and aging is less investigated." (PMID 40011442, 2025). "However, the changes in ATF3 activity in metabolic syndrome remain unclear." (PMID 37049617, 2023). "To examine whether ATF3 modulates energy metabolism and body-weight changes in mice, we analyzed the metabolic syndrome and its related traits in ATF3-null (ATF3−/−) mice." (PMID 31667363, 2019). "Although, enhanced expression of activating transcription factor 3 has been reported to play a role in diabetic angiopathy, in stress-induced beta cell dysfunction and hepatic LDL receptor down-regulation, its cardiac role in metabolic syndrome has not been implicated yet." (PMID 23320804, 2013).
osteoarthritis (11 papers, 2013 to 2025). A noninflammatory degenerative joint disease occurring chiefly in older persons, characterized by degeneration of the articular cartilage, hypertrophy of bone at the margins and changes in the synovial membrane. "The number of Atf3+ sensory neurons 3 weeks after induction of osteoarthritis in two separate models was reduced by treatment with an LPA receptor inhibitor." (PMID 41322115, 2025). "The verification result showed that the expression levels of IL6, VEGFA, JUN, IL-1β, and ATF3 were significantly increased in osteoarthritis samples (p < 0.05)." (PMID 30186872, 2018). "Our result is also consistent with reports of ATF-3 induction in lumbar DRGs by mono-iodoacetate-induced osteoarthritis, a model of joint in inflammation that produces concurrent axonal damage required to drive ATF-3 induction." (PMID 24223534, 2013). "Indeed, the initial proposition for “nociplastic” specifies osteoarthritis as a suitable example condition, and expression of Atf3 in sensory neurons is induced in animal models of osteoarthritis." (PMID 41322115, 2025). "In diseases such as osteoporosis and osteoarthritis, Atf3 expression is upregulated." (PMID 39430747, 2024). "Meanwhile, several studies have shown that ATF3 knockdown could alleviate the progression of osteoarthritis, while some studies have shown that ATF3 is a highly conserved regenerative transcription factor in the vertebrate nervous system." (PMID 36819777, 2023). "Additionally, targeting and inhibiting Atf3 may block the progression of bone-destructive diseases such as osteoarthritis." (PMID 39430747, 2024). "Through bioinformatics analysis, eight hub genes (ATF3, EGR1, FOSB, FOSL1, FOSL2, JUN, JUNB, and MYC) were identified as potential regulators of osteoarthritis (OA) iron-death-related genes." (PMID 39564502, 2024). "MiR-34-5P has been demonstrated to interact with ATF3, IL6, IL1B, and EGR1—an iron death-related gene identified in osteoarthritis (OA) synovial tissue—among others, potentially contributing to the pathogenesis of iron death." (PMID 39564502, 2024).
type 2 diabetes (11 papers, 2011 to 2025). "The Atf3 gene is associated with the induction of type 2 diabetes and alcohol consumption-induced metabolic impairment and thus may be the major negative regulator for glucose homeostasis." (PMID 25074928, 2014). "Significance: The presented data uncover a new role for Atf3 as a potential therapeutic target in treating type 2 diabetes." (PMID 25074928, 2014). "ATF3 expression has been reported up-regulated in insulitis and type 1 or type 2 diabetics." (PMID 21689475, 2011). "Detection of increased ER stress marker expression including ATF3, Bip and CHOP in mouse islets exposed to elevated lipids and high glucose and in β-cells of type 2 diabetic patients supports the involvement of ER stress in the pathogenesis of Type 2 diabetes." (PMID 24475223, 2014).
injury (10 papers, 2012 to 2025). Damage inflicted on the body as the direct or indirect result of an external force, with or without disruption of structural continuity. "Taken together, ATF3 has firmly emerged as a potential therapeutic target in acute brain injury." (PMID 41250979, 2025). "Numerous studies have shown that activating transcription factor 3 (ATF3) could be used as a neuronal marker of nerve injury, whereas calcitonin gene-related peptide (CGRP) is a marker of nociceptive information transmission in the DRG and spinal cord." (PMID 26819761, 2016). "Following nerve trauma, a number of neurochemical changes that have been linked to neuropathic pain mechanisms occur within DRG neurons, including the neuronal injury marker activating transcription factor-3 (ATF-3), neuropeptide Y (NPY), galanin and growth-associated protein-43 (GAP-43)." (PMID 25070481, 2015). "Activating transcription factor 3 (ATF3) is a stress-induced transcription factor and a familiar neuronal marker for nerve injury." (PMID 36768628, 2023). "Beyond direct regulation of Cbln2, SOX11 may influence broader transcriptional programs through interactions with downstream factors such as ATF3 and c-JUN, both of which are well-established contributors to neuropathic pain following nerve injury." (PMID 41162740, 2025). "Activating transcription factor 3 (ATF3) is a marker of stress-induced nerve injury, and neuropeptide Y (NPY) is a 36-amino-acid neuropeptide that is significantly upregulated after nerve injury." (PMID 35821338, 2023). "Molecular pathways such as cAMP, MAPK, JAK/STAT, ATF3/CREB, BMP/SMAD, AKT/mTORC1/p70S6K, PI3K/AKT, GSK-3β/CLASP, BDNF/Trk, Ras/ERK, integrin/FAK, RhoA/ROCK/LIMK, and POSTN/integrin are activated after nerve injury and are considered significant players in axonal regeneration." (PMID 36551942, 2022). "In our study, neither electrical nor optogenetic stimulation led to a significant ATF3 expression increase in the DRG neurons compared to controls, suggesting that the stimulation remains without notable nerve injury." (PMID 40705704, 2025).
ischemia (10 papers, 2015 to 2025). A hypoperfusion of the BLOOD through an organ or tissue caused by a PATHOLOGIC CONSTRICTION or obstruction of its BLOOD VESSELS, or an absence of BLOOD CIRCULATION. "Whereas, with the loss-of-function approach, ATF3 knockout (KO) mice showed bigger infarct and worse functional outcome after ischemia." (PMID 36768628, 2023). "In fact, this study revealed that ATF3 upregulation might be related to mechanisms underlying mitigation of the neurotoxicity at an early stage after ischemia." (PMID 36707762, 2023). "In light of these antecedents and the gaps in our understanding of how ATF3 influences microglia activation, the main aim of this study was to evaluate the possible contribution of ATF3 loss to the microglia activation and neuronal apoptosis that takes place in the brain after ischemia." (PMID 35263513, 2022). "To date, most of the previous studies have been focused on the role of ATF3 against ischemia-induced inflammatory response." (PMID 36768628, 2023). "Ccl2 was also elevated in Atf3 mutants during cerebral ischaemia indicating a more general mechanism of Ccl2 inhibition by ATF3." (PMID 27581653, 2016). "It was found that administration of the epithelium-derived exosomal ATF3 (activating transcription factor 3) mRNA attenuates ischemia/reperfusion-induced kidney injury by inhibiting monocyte chemotactic protein-1 (MCP-1)-induced macrophage infiltration." (PMID 26539435, 2015). "ATF3 overexpression may provide a new therapeutic intervention for ischemia-mediated retinal injury." (PMID 41181154, 2025). "Furthermore, when Ad-ATF3 was administered immediately after 35 min of MCA occlusion (namely post-ischemia, at the onset of reperfusion), the infarct volume determined at 24 h of reperfusion was also significantly reduced in the Ad-ATF3 treated group as compared to the Ad-hPGK control." (PMID 36768628, 2023). "Simultaneously, ATF3 enhances cellular antioxidant capacity by regulating the expression of SLC7A11, alleviating intestinal ischemia-reperfusion injury and inhibiting ferroptosis." (PMID 41550926, 2025). "ATF3/CCL2 was mainly expressed on activated microglia; thus, ATF3/CCL2 may be involved in microglia activation in the brain after ischemia." (PMID 35263513, 2022).
peripheral nerve injury (10 papers, 2012 to 2025). Injury to a peripheral nerve. "Peripheral nerve injuries cause a transcriptional response in sensory neurons that is regulated by Atf3 (activating transcription factor 3) and is essential for functional recovery." (PMID 38463961, 2024). "Peripheral nerve injury after CCI intervention is demonstrated to cause the release of activating transcription factor-3 (ATF3) and caspase-6 from axonal terminal, which then acts on microglia to trigger their activation." (PMID 35592413, 2022). "In DRG neurons, activation of c-Jun and induction of ATF-3 are events, which are associated with survival and axonal outgrowth following a peripheral nerve injury." (PMID 24877090, 2014). "ATF3 is highly induced in all injured DRG neurons after peripheral nerve injury, and the increase in the number of ATF3-positive DRG neurons is correlated positively with pain behavior." (PMID 22909213, 2012). "Single-nucleus genomics have revealed that, within hours of injury, the upregulation of Atf3 and Jun could be detected in neurons following peripheral nerve injury." (PMID 34955748, 2021). "Activating transcription factor 3 (ATF3) expression in DRG neurons, a marker of peripheral nerve injury, is transiently expressed in the 1 mg MIA model." (PMID 24206615, 2013). "It has been suggested that transcription factors such as ATF3, JUN and SOX11 may be important in the regulation changes in ion channel function and their accessory subunits after peripheral nerve injury." (PMID 31620455, 2019).
squamous cell carcinoma (10 papers, 2008 to 2024). A carcinoma arising from squamous epithelial cells. "ATF3 regulates the biological behavior of human squamous cell carcinoma through the downregulation of IFI27." (PMID 38226966, 2024). "A recent study showed that TSA induces p21 expression via the down-regulation of ATF3 in A431 epidermoid carcinoma cells." (PMID 30939155, 2019). "In a transgenic mouse model in which human ATF3 is expressed from the bovine cytokeratin 5 promoter (BK5.ATF3), we reported spontaneous development of oral tumors, including about a 70% incidence of squamous cell carcinomas at 16 months of age." (PMID 21304988, 2011). "ATF3 has been shown to enhance the apoptotic effect of curcumin in squamous cell carcinoma cells and to mediate nitric oxide-induced apoptosis in pancreatic beta cells." (PMID 21034493, 2010). "We and others have shown that ATF3 is capable of binding to the NOXA promoter in other tumor contexts (e.g., squamous cell carcinoma of the head and neck) after other exposures, such as cisplatin." (PMID 39302104, 2024).